VIM (vimentin)
Diseases named in the same sentence as VIM in open-access papers (continued):
Sharing a sentence is not in itself a finding about the gene and the disease.
gastric cancer (continued). "Increased TGF-β1 expression was accompanied by nuclear localization of NF-κB-p65 and higher levels of the mesenchymal marker vimentin in human gastric cancer samples." (PMID 26176983, 2015). "Immunofluorescence assay indicated that knocking down AIB1 expression in gastric cancer cells substantially increased the expression of epithelial cell marker E-cadherin and reduced the expression of mesenchymal marker vimentin." (PMID 25970779, 2015). "Knockdown of RUNX3 promoted cell invasion and increased the protein expression of the mesenchymal marker vimentin in human gastric cancer cells." (PMID 24447545, 2014). "Here, we report that FOXO4 repress cell proliferation and metastasis in gastric cancer by the regulation G1 cell-cycle arrest and vimentin." (PMID 24886657, 2014). "The main findings of this study are summarized as follows: 1) H. pylori CagA is responsible for induction of TWIST1 or vimentin and inhibition of E-cadherin in gastric cancer cells." (PMID 25144746, 2014). "We knocked down miR-30a with an inhibitor of miR-30a in RUNX3-overexpressed gastric cancer cells and detected cell invasion and the expression of vimentin." (PMID 24447545, 2014). "In gastric cancer patients, levels of RUNX3 were positively correlated with miR-30a and negatively associated with the levels of vimentin." (PMID 24447545, 2014). "Overexpression of RUNX3 suppressed cell invasion and decreased the protein expression of vimentin in the cells and inhibited gastric cancer cells colonization in nude mice." (PMID 24447545, 2014). "The addition of MG132 did not abolish the ability of ectopically expressed RUNX3 to decrease vimentin protein level in gastric cancer cells." (PMID 24447545, 2014). "Knockdown of RUNX3 promoted the EMT and increased the protein expression of the mesenchymal marker vimentin in human gastric cancer cells." (PMID 24447545, 2014). "Overexpression of RUNX3 suppressed cell invasion and decreased the protein expression of vimentin in gastric cancer cells and inhibited gastric cancer cell colonization in nude mice." (PMID 24447545, 2014). "EMT, as evidenced by drastic changes in cell morphology and reversal of the expression of epithelial markers (E-cadherin and β-catenin) and mesenchymal markers (vimentin and fibronectin), was activated in RhoGDI2-overexpressing gastric cancer cells." (PMID 24721928, 2014). "In gastric cancer, VIM, which has been known to be a methylation marker, was also hypermethylated, and it centered in the network interaction with other proteins, such as PDGF complex and TWIST1." (PMID 24842468, 2014). "In gastric cancer patients, levels of RUNX3 were positively correlated with miR-30a and negatively associated with vimentin." (PMID 24447545, 2014). "Previous research has suggested that CAFs in human gastric cancer tissues not only express fibroblast-labeled vimentin, but also the myofibroblast markers SMA and FAP." (PMID 23420648, 2013). "Enhanced expression of snail, twist, vimentin have been reported in human gastric cell lines infected by H. pylori and in a gastric carcinoma mouse model." (PMID 23565224, 2013). "The expression of CD146 and three epithelial-mesenchymal transition (EMT)-related proteins (E-cadherin, β-catenin and vimentin) was examined in 144 gastric cancers by immunohistochemistry." (PMID 22754372, 2012). "In conclusion, NDRG1 knockdown induced the upregulation of E-cadherin and downregulation of vimentin and Snail, and suppressed the invasion, metastasis and accumulation of ascites by the highly metastatic gastric cancer cells." (PMID 22844455, 2012). "Cag-positive H. pylori significantly upregulate the EMT-associated genes Snail, Slug and vimentin in association with the induction of MMP-7, suggesting a role for these proteins in gastric cancer development." (PMID 22662230, 2012). "This NDRG1 mediated regulation of E-cadherin and/or vimentin expression affected epithelial mesenchymal transition of gastric cancer cells." (PMID 22844455, 2012).
gastric cancer (continued). "Norepinephrine (NE) induced the EMT process in gastric cancer cells through β2-AR-HIF-1α-SNAIL activity, reduced E-cadherin expression, and enhanced the EMT markers, such as vimentin, which further promoted the invasiveness and migration of gastric cancer cells." (PMID 39941895, 2025). "Compared with the blank group, the co culture group of two gastric cancer cell lines M2c showed a significant decrease in E-cadherin protein, a significant increase in N-cadherin protein, a significant increase in Vimentin protein." (PMID 39991579, 2025). "Vimentin positivity in gastric cancer suggests a highly invasive phenotype and may play a crucial role in the metastasis of gastric carcinoma." (PMID 40761980, 2025). "Furthermore, the lncRNA LINC00675 regulates phosphorylation of vimentin on Ser83 and thus impinges on gastric cancer progression." (PMID 38311781, 2024). "Therefore, exploring the specific mechanism of different phosphorylation sites of VIMENTIN can improve the theoretical basis of gastric cancer metastasis." (PMID 38459513, 2024). "According to our experiments and analysis, circGLIS3 overexpression can reduce the phosphorylation of VIMENTIN at Ser83, revealing the specific mechanism by which circGLIS3 reduces the phosphorylation level of VIMENTIN to promote the invasion and metastasis of gastric cancer." (PMID 38459513, 2024). "Thus, we proved that circGLIS3 can reduce the phosphorylation of vimentin Ser83 to promote the invasion and metastasis of gastric cancer." (PMID 38459513, 2024). "Interestingly, very recently vimentin expression in tumor stroma was postulated as a potential prognostic marker for canine gastric cancer, supporting our observations." (PMID 37568772, 2023). "Moreover, gastric cancer cells treated with palmitic acid decreased the expression of p-STAT3, p-JAK2, N-cadherin and vimentin indicating that palmitic acid inhibited the growth of gastric cancer by blocking the STAT3 signaling pathway." (PMID 37240342, 2023). "Ultimately, CM-DOP inhibited the migration of gastric cancer cells by reversing the effects of N-cadherin and vimentin, as well as increasing the E-cadherin expression; meanwhile, CM-DOP upregulated Caspase-3 and increased the ratio of Bax/Bcl-2, thereby inducing apoptosis." (PMID 37894541, 2023). "Under the condition of coculture of macrophages, the downregulation of CDK5RAP3 resulted in a significant upregulation of the expression levels of N-cadherin, vimentin and Snail mRNA in gastric cancer, while the expression level of E-cadherin was significantly reduced." (PMID 35999359, 2023). "Indeed, knocking down NDRG1 in gastric cancer cells increased E-cadherin expression and suppressed the expression of vimentin; linking the typically high NDRG1 levels to the metastatic potential of gastric cancer cells." (PMID 36497221, 2022). "In addition, the co-expression of FoxK1 and vimentin promotes the metastasis of gastric cancer cells by inducing EMT." (PMID 35903069, 2022). "NETs promoted the migration of gastric cancer cells and induced epithelial-to-mesenchymal transition by downregulation of E-cadherin and enhanced expression of vimentin in a human gastric cancer cell line, and this was abrogated after addition of DNase-1 or PAD4-inhibitor." (PMID 35979369, 2022). "Similarly, MicroRNA-1275 regulated Vimentin and E-cadherin to inhibit the migration and invasion of gastric cancer cells." (PMID 35201521, 2022). "Similarly, H. pylori significantly upregulates vimentin in the gastric cancer cell lines as well as increases the expression of MMP-7." (PMID 34827233, 2021). "Meanwhile, Vimentin was principally expressed in the cell cytoplasm of gastric cancer tissues." (PMID 35003354, 2021). "Notably, the epithelial cell marker E-cadherin was upregulated in Mist1-overexpressing gastric cancer cells; however, the mesenchymal marker N-cadherin, Vimentin and E-cadherin repressor Snail were downregulated." (PMID 34149921, 2021).
gastric cancer (continued). "that CircNHSL1/miR-1306-3p/SIX1 axis could affect the development and progression of gastric cancer by cooperating with Vimentin and EMT." (PMID 33726765, 2021). "For example, Dong and his colleagues combined their data with TCGA database, showing that NDRG1 regulated EMT‐associated protein expression (Twist1, Snail, VE‐cadherin and vimentin decreased, whereas E‐cadherin increased) in gastric carcinoma, which is negatively correlated with poor prognosis." (PMID 34965023, 2021). "Our data showed that BAG2 knockdown might suppress intercellular EMT process by down-regulating the expression of N-cadherin, MMP9, Vimentin and Snail, thereby reducing invasion and migration of gastric cancer cells." (PMID 32082999, 2020). "TQ also inhibited cell migration ability of MGC-803 and SGC-7901 gastric cancer cells by Akt-dependent downregulation of the expression of mesenchymal genes (N-cadherin, Vimentin, and Twist) and upregulation of the expression of epithelial genes such as E-cadherin and cytokeratin-19." (PMID 33167519, 2020). "In addition, overexpression of CDC27 induces invasion and migration by gastric cancer cells, which is associated with downregulation of the EMT-related biomarker E-cadherin and upregulation of vimentin." (PMID 32710728, 2020). "Moreover, cordycepin was found to inhibit the gastric cancer cells metastasis by activating an expression of epithelial marker such as E-cadherin and inhibiting mesenchymal marker such as Vimentin and E-cadherin repressors, including Snail and Slug." (PMID 33167519, 2020). "LINC00675 enhances the phosphorylation of vimentin on Ser83 to suppress gastric cancer progression." (PMID 32795333, 2020). "In gastric cancer, overexpressed CORO1C is associated with poor prognosis and could promote metastasis by regulating cyclin D1 and vimentin." (PMID 32695668, 2020). "Vimentin was determined to acted as a poor prognostic factor in patients with gastric cancer." (PMID 30974047, 2019). "As cyclin D1 and vimentin play an oncogenic role in gastric cancer, CORO1C may exert its tumor‐promoting activity through these proteins." (PMID 30974047, 2019). "Taken together, circNHSL1 promotes gastric cancer progression by miR-1306-3p/SIX1/Vimentin axis." (PMID 31438963, 2019). "We also found that eIF3b could affect the expression of β-catenin and vimentin in gastric cancer cells." (PMID 31423012, 2019). "Therefore, high levels of cyclin D1 or vimentin indicated poor prognosis in gastric cancer patients." (PMID 30974047, 2019). "The CORO1C–Rac‐1–cyclin D1–vimentin pathway might also contribute to human gastric cancer and mediate the enhanced carcinogenicity of gastric cancer cells, which needs to be examined in future work." (PMID 30974047, 2019). "Finally, in gastric cancer cells HSF1 overexpression stimulates vimentin, N-cadherin, and Snail1 expression, and decreases the level of E-cadherin." (PMID 31752429, 2019). "Notably, when we co-cultured NCI-N87 gastric cancer cells with normal fibroblasts at various cell-to-cell concentrations, we observed a significant correlation between EpCAM and vimentin fluorescent intensity levels." (PMID 31850215, 2019). "Furthermore, miR-1306-3p reversed the ability of circNHSL1 to enhance mRNA and protein expression of SIX1 and Vimentin in gastric cancer cells." (PMID 31438963, 2019). "Furthermore, another study revealed that FBXW7 inhibited the metastasis and progression of gastric cancer partly via the RhoA signaling pathway, which was accompanied by upregulation of E-cadherin and downregulation of N-cadherin and vimentin." (PMID 30999935, 2019). "Furthermore, knockdown of LOX increased E-cadherin and decreased vimentin expression in gastric cancer." (PMID 31752264, 2019). "Vimentin-positive gastric carcinomas with rhabdoid features are also known to have a poor prognosis, although the prognosis of vimentin-positive carcinoma is still unknown." (PMID 30649642, 2019).
gastric cancer (continued). "Our study also indicated that SNX1 was associated with EMT in gastric cancer cells as it showed that overexpression of SNX1 in GC cells inhibited migration and invasion, and led to upregulation of E-cadherin and downregulation of Vimentin and Snail." (PMID 29868263, 2018). "In addition, the level of E-cadherin was increased and vimentin was decreased in miR-612-overexpressing gastric cancer cells." (PMID 30021604, 2018). "Vimentin might also contribute to an invasive phenotype in gastric cancer, which means that it is potentially useful as a biomarker to define cancer aggressiveness." (PMID 30248895, 2018). "Furthermore, positivity for SPOCK1, Slug or Vimentin expression negatively correlated with post‐operative overall survival in patients with gastric cancer (P < 0.05, respectively)." (PMID 28940639, 2018). "Furthermore, silencing of TIMP2 significantly increased EMT makers including N-cadherin and Vimentin, while decreased E-cadherin expression in gastric cancer cells." (PMID 29220395, 2017). "Similarly, treatment of quiescent gastric cancer stem cells with IL‐17 also results in EMT‐like changes including E‐cadherin loss, de novo vimentin acquisition, and increased migratory and invasive properties and associates with STAT3 phosphorylation." (PMID 28599100, 2017). "Notably, expression of CLND1, β-catenin and Vimentin proteins was increased in gastric cancer tissue from patients with TNM stage II or III." (PMID 27333045, 2016). "Next, we determined the expression of NKX6.3, E-cadherin, N-cadherin, β-catenin, p-GSK3βY216, CLND1, RhoA, Cdc42, Rac1/2/3, Snail, Slug and Vimentin proteins in 7 gastric cancer tissues at different TNM stages and compared with expression in non-tumorous gastric mucosal tissues." (PMID 27333045, 2016). "Following IGF-I treatment, both western blotting and immunofluorescence observed obvious EMT marker switching, as shown by the downregulation of the epithelial marker E-cadherin and the upregulation of the mesenchymal marker vimentin in BGC-823 gastric cancer cells (P<0.05)." (PMID 25435948, 2015). "E-cadherin and vimentin are regulated by β-catenin during EMT in gastric cancer." (PMID 26563263, 2015). "Moreover, decreased levels of HOTAIR expression resulted in significant increased expression of E-cadherin but decreased expression of N-cadherin and vimentin in gastric cancer cells." (PMID 26136075, 2015). "Finally, we determined RUNX3 and vimentin expression in 55 primary tumour samples from gastric cancer patients by western blot analysis and miR-30a expression by qRT-PCR analysis." (PMID 24447545, 2014). "Therefore, RUNX3 downregulated vimentin and inhibited gastric cancer cell invasion through an miR-30a–dependent mechanism." (PMID 24447545, 2014). "Therefore, we investigated the expression of the epithelial and mesenchymal markers E-cadherin and vimentin, respectively, in gastric cancer cells transfected with control siRNA and RUNX3 siRNA." (PMID 24447545, 2014). "In addition, positive vimentin expression could serve as a poor prognostic marker in gastric cancer." (PMID 40761980, 2025). "Likewise, overexpression of ACAT1 inhibited epithelial mesenchymal transition (EMT) in gastric cancer cells evidenced by increased expression of the epithelial marker E-Cadherin, decreased expression of mesenchymal marker vimentin, and decreased expression levels of SNAI 1/3." (PMID 39247186, 2024). "For example, the downregulation of miR-320a increases the stability of vimentin in gastric cancer (GC) cells by enhancing USP14, thus upregulating vimentin and promoting GC cell growth, migration, and invasion." (PMID 37917013, 2023). "In addition, this study identified that radiation combined with PF treatments overcomes radioresistance and mediates apoptosis and cell death via the regulation of EMT makers, such as E-cadherin, N-cadherin, and vimentin, in gastric cancer cells and radiation-resistant gastric cancer cells." (PMID 38140352, 2023).
gastric cancer (continued). "Therefore, the promoting role of CORO1C in both proliferation and metastasis of gastric cancer cells might be mediated by cyclin D1 and vimentin." (PMID 30974047, 2019). "Therefore, cyclin D1 and vimentin might mediate the process of CORO1C increasing oncogenicity in human gastric cancer cells." (PMID 30974047, 2019). "Thus, RUNX3 suppressed gastric cancer cell invasion and vimentin expression by activating miR-30a." (PMID 24447545, 2014). "Exome sequencing of the CD45+Vimentin- cells (normal hematopoietic fraction) and the CD45-Vimentin+ cells (CTC fraction) were carried out, and 102 neoantigens were identified using the Ancer platform in the patient with gastric cancer." (PMID 40718490, 2025). "Our findings demonstrate that increased NINJ2 expression in chemoresistant gastric cancer cells leads to upregulation of CD44, which in turn promotes vimentin expression and enhances invasive and mesenchymal characteristics." (PMID 40518514, 2025). "Previous studies have reported that CD44 directly induces vimentin gene transcription via EMT transcription factors like Slug, thereby facilitating EMT and metastatic progression in gastric cancer." (PMID 40518514, 2025). "Hp cytotoxin-associated gene A (Cag A) reduced the expression of E-cadherin and enhanced the expression of vimentin and TWIST1, thereby describing new EMT signaling pathways in gastric cancer cell lines." (PMID 39941895, 2025). "In vitro studies have demonstrated that JPYZXZ inhibits the motility of gastric cancer cells, reduces tumor cell viability, and decreases the expression of EMT markers such as N-cadherin and Vimentin, while increasing E-cadherin expression." (PMID 40765835, 2025). "Among them, phosphorylation and structural rearrangement of different VIMENTIN sites play an important role in the EMT process, and enhanced phosphorylation of the VIMENTINser83 site can inhibit the invasion and migration of gastric cancer." (PMID 38459513, 2024). "In gastric cancer, we found that AMBRA1-KO dramatically reduced the levels of vimentin and N-cadherin and increased the expression of E-cadherin." (PMID 39720719, 2024). "In gastric cancer, AQP3 induced EMT by modulating the expression of known EMT markers, including vimentin and β-catenin." (PMID 39857360, 2024). "RRAD inhibition could also suppress expression of EMT-associated proteins (VIMENTIN, TWIST, SNAIL, and OCCLUDIN), VEGF, and ANGP2 in gastric cancer (GC) and colorectal cancer (CRC) cell lines." (PMID 36979412, 2023). "We demonstrated that PA treatment for 12 h decreased the expressions of p-STAT3, p-JAK2, N-cadherin, and vimentin, and inhibited the nuclear expression of p-STAT3 in gastric cancer cells." (PMID 36672337, 2023). "In summary, our study first discovered the malignant tumor-promoting role of LAD1 in gastric cancer and discovered a novel mechanism of LAD1 inhibiting the ubiquitination of Vimentin mediated by MAEA." (PMID 37718450, 2023). "The overexpression of carnitine palmitoyltransferase 1A (CPT1A), an essential enzyme for FAO, increases vimentin and SNAIL and decreases E-cadherin expression in gastric cancer." (PMID 38002286, 2023). "C11_VWF were characterized by co‐expressing marker genes of fibroblasts (COL1A1, FAP, VIM, ACTA2) and endothelial cells (VWF, PECAM1, CLDN5, FLT1, RAMP2), which resembled a subgroup of cells undergoing an EMT transition in gastric cancer." (PMID 38115703, 2023). "In gastric cancer, LINC00675 enhanced the phosphorylation of vimentin on Ser83, while in colorectal cancer, LINC00675 inhibited the development of colorectal cancer by sponging miR-942 and regulating Wnt/β-catenin signaling." (PMID 37074188, 2023). "In multiple gastric cancer datasets, TGFβ were positively correlated with EMT score and mesenchymal markers (CDH2, VIM and ZEB1), while significantly negatively correlated with epithelial marker CDH1." (PMID 36119489, 2022).